EPO (erythropoietin)
Diseases named in the same sentence as EPO in open-access papers (continued):
Sharing a sentence is not in itself a finding about the gene and the disease.
renal failure (continued). "EPO has historical usage in anemic patients with renal failure and is thus considered safe to use in humans." (PMID 33920974, 2021). "In the present study, the effects of the combination of VD3 and EPO in I/R acute kidney injury were studied." (PMID 33953855, 2021). "While recombinant human EPO increases platelet count in patients suffering from renal failure, in vitro studies have indicated the stimulatory effect of EPO on megakaryocytic proliferation, in combination with other megakaryocytic cytokines such as TPO." (PMID 34440444, 2021). "In patients, the data of EPO administration and the disease characteristics in patients with sepsis-induced acute kidney injury (sepsis-AKI) were evaluated." (PMID 34831360, 2021). "The reasons of which include insufficient erythropoietin secretion, inadequate iron intake, hemorrhage, chronic inflammation, vascular endothelial damage, and hemodynamic disorder induced by renal failure, dialysis, and infection." (PMID 32722980, 2020). "More specifically, EPO can prevent the development of renal failure during the end-stages of various renal diseases, and can actively control the fibrosis of renal interstitial tissue." (PMID 32154256, 2020). "Renal failure results in disturbed renal metabolic activities with reduced renin, erythropoietin, and vitamin D production, which adversely affects the immune system." (PMID 32635646, 2020). "Extensive research during recent years demonstrated that EPO can improve recovery from acute kidney injury." (PMID 32154256, 2020). "Subsequent to this relaxation of erythropoietin administration criteria, the Hct levels for both prevalent and incident peritoneal dialysis patients increased from 28%-29% to 30%-31%." (PMID 33331829, 2020). "It is known that inflammation is associated with reduced production of RBC20 and studies of patients with renal failure have reported reduced responsiveness to treatment with EPO in those with low-grade inflammation." (PMID 31700048, 2019). "In patients with renal failure, damaged kidneys cannot produce adequate erythropoietin, a humoral factor promoting proliferation and maturation of erythroid cells, and consequently hemoglobin synthesis is downregulated." (PMID 31598113, 2019). "EPO levels of patients with less severe renal insufficiency were substantially higher than those with CKD 5 (Kantorovich distance: 22.73)." (PMID 29668766, 2018). "Encouraged by these results erythropoietin was injected intravenously in humans before surgery, and was able to reduce the incidence of acute kidney injury in patients who underwent a coronary artery bypass." (PMID 26791565, 2016). "EPO enhances regeneration of the tubular epithelium via its anti-apoptotic and anti-inflammatory features, prevents acute kidney injury (AKI), and improves postoperative renal function when administered in a preventive fashion." (PMID 25998259, 2015). "Experimental evidence suggests that erythropoietin (EPO) attenuates renal damage in acute kidney injury." (PMID 25643790, 2015). "In a model of renal failure due to ischemia followed by gentamicin, improvement in renal function and structure has been found using adult renal cells enriched for erythropoietin producing cells." (PMID 26136112, 2015). "A study in a previous issue of Critical Care examining the ability of erythropoietin to prevent or ameliorate acute kidney injury in patients undergoing complex valvular heart surgery is similarly negative." (PMID 25672222, 2014). "The effect of BAY 85-3934 on the induction of endogenous EPO production was evaluated in an animal model of impaired kidney function, the gentamicin-induced kidney failure model." (PMID 25392999, 2014). "Recent publications have suggested reno-protective actions for EPO in certain models of acute kidney injury in rats." (PMID 25340147, 2013).
renal failure (continued). "Evaluation of 4-h CCl was a planned component of the two-centre Early intervention in Acute Renal Failure (EARLYARF) randomised controlled trial of high dose erythropoietin for the prevention of AKI in the ICU." (PMID 22713519, 2012). "This contrasts with a recent study where erythropoietin given at the time of operation was efficient in preventing acute kidney injury, reducing ICU stays and decreasing mortality in cardiac surgery patients." (PMID 23033926, 2012). "EPO also is protective against medication-induced renal dysfunction, facilitating the recovery from cisplatin-induced acute kidney injury and attenuation of renal interstitial inflammation and fibrosis in chronic cyclosporine nephropathy." (PMID 21943500, 2011). "A more extensive trial is required, with valid biomarkers/endpoints, to determine efficacy of EPO in acute kidney injury." (PMID 21943500, 2011). "Taken together, these results indicate that EPO-hyFc(H) is highly effective in restoration from acute renal failure through active erythropoiesis." (PMID 21957455, 2011). "Erythropoietin gene therapy would be an alternative to treatment with recombinant Epo in patients with kidney failure." (PMID 20376311, 2010). "The haematopoietic growth factor erythropoietin (EPO) has been in clinical use for over 20 years to treat patients with anaemic conditions, ranging from renal failure to cancer." (PMID 19586522, 2009). "An elevation of platelet count was observed in animal studies and in patients with renal failure receiving erythropoietin as medication." (PMID 18380894, 2008). "In our cohort of patients, erythropoietin was newly prescribed almost exclusively in acute renal failure requiring dialysis and transfusion." (PMID 17002795, 2006). "The extensive knowledge obtained in animal models and in humans that the kidney is the organ responsible for producing EPO led to the realization that patients with renal failure undergoing chronic dialyses are anemic because their kidney is no longer capable of producing the hormone." (PMID 38672425, 2024). "One last story to put things into perspective recalled by John is that Dr. George Rathmann, who headed Amgen at the time of the EPO trial, was diagnosed with myeloma later in life and eventually developed renal failure and was the beneficiary of his own company’s product." (PMID 38672425, 2024). "Based on this information, Dr. Joseph Eschbach, a nephrologist with a large patient practice in Seattle, and John conceived the hypothesis that “kidney failure” represents the ideal disease model to test recombinant EPO as “hormone replacing therapy”." (PMID 38672425, 2024). "There is insufficient evidence to support the use of erythropoietin in the absence of erythropoietin deficiency and/or renal failure." (PMID 36823529, 2023). "The role of erythropoietin is unclear or not recommended unless there is documented renal failure and/or erythropoietin deficiency." (PMID 36823529, 2023). "EPO significantly enhanced the recovery from acute renal failure induced by cisplatin in rats." (PMID 37511089, 2023). "In addition, previous study showed that M-CSF inhibits the growth of erythroid progenitor cells in patients with renal failure who were undergoing hemodialysis, probably by reducing their sensitivity to erythropoietin." (PMID 31419967, 2019). "Renal failure affects the formation of erythropoietin and thereby affects hematopoietic function." (PMID 29422012, 2018). "The downregulated EPO-R may be related to inflammation and oxidative stress and is a putative mechanism of EPO resistance in patients with heart and kidney failure." (PMID 30357563, 2018). "Of the eight substances that might reduce inflammation and reduce cytotoxicity they focused on, only two were tested in clinical studies for acute kidney injury (statins and erythropoietin)." (PMID 26791565, 2016). "Administration of EPO protected swine from postresuscitation acute kidney injury." (PMID 27847811, 2016).
renal failure (continued). "Renal insufficiency determined by serum creatinine level of >1.5 mg/dL, estimated glomerular filtration rate <60 ml/minute/1.73 m2, and erythropoietin levels was also observed to be high in the cases (54.0 %; with mean creatinine concentration of 3.43±1.73 and erythropoietin 6.35±1.28 mIU/mL)." (PMID 27142617, 2016). "Erythropoietin production/secretion declines with advancing renal failure in all cases of CKD, regardless of cause, hence the similarity in prevalence across the different settings." (PMID 26407219, 2015). "While EPO treatment resulted in a further increase of HO-1 mRNA levels in concordance with previous findings in experimental models of kidney failure and myocardial infarction, HO-1 activity, a more specific assessment for functional properties, was not further enhanced." (PMID 26380246, 2015). "A recent retrospective cohort study has also suggested that erythropoietin treatment may slow the progression of renal failure." (PMID 25340147, 2013). "EPO improves CP-induced acute renal failure and leads to recovery after tubular damage." (PMID 23227363, 2012). "EPO is one of these agents used for treatment of anemia and acute renal failure induced by CP." (PMID 23227363, 2012). "Accumulating evidence, however, suggests that EPO has additional organ protective effects, which may be useful in the prevention or treatment of acute kidney injury." (PMID 21906325, 2011). "However, in this case investigators preferred to do it in the target patients since their renal failure condition would have considerable influence on EPO pharmacokinetics and pharmacodynamics." (PMID 15910687, 2005). "For individuals with renal failure, erythropoietin administration may be beneficial." (PMID 38792906, 2024). "Consequently, manipulating the hypoxia signaling pathway in osteoblasts to boost EPO production may hold promise, especially in cases of renal insufficiency where traditional renal EPO production is compromised." (PMID 38764792, 2024). "Recent studies discovered that EPO might efficiently protect against renal failure." (PMID 37511089, 2023). "Erythropoietin, vitamin D and uromodulin are known to mediate kidney–immune crosstalk and their disrupted production could impact morbidity and mortality in sepsis with acute kidney injury." (PMID 35163625, 2022). "Although the related researches on the relationship between renal insufficiency and hypoxemia are limited and the exact mechanisms remain to be further investigated, we guess that inflammatory responses, erythropoietin production by the kidney, and the subsequent oxygen delivery may be involved." (PMID 35990967, 2022). "An elegant model proposed by Koury and Bondurant (1992), explained the basis of differing EPO sensitivities as a built-in mechanism to prevent all erythroid precursors undergoing apoptosis during low EPO levels in circulation such as in patients with renal failure." (PMID 32457644, 2020). "Therefore, in the present study, we determined whether EPO could exert an impact on the dynamics of macrophages in a well-established model of rhabdomyolysis-induced acute kidney injury and explored the potential mechanisms." (PMID 28383559, 2017). "The EARLYARF trial was the first prospective, randomized, double-blind, placebo-controlled, parallel-group trial to study whether early treatment with EPO (500 IU/kg within 6 hours and again 24 hours later) could prevent the development of acute kidney injury in patients." (PMID 21943500, 2011). "A recombinant human erythropoietin activates serum FGF23 in mice with normal kidney function and acute kidney injury." (PMID 35622784, 2022). "Upon acute kidney injury (AKI), fibroblasts detach from the capillaries and migrate to the site of damage, where they transdifferentiate to myofibroblasts, losing erythropoietin expression but gaining the ability to secrete scar-associated ECM." (PMID 32562113, 2020).
renal failure (continued). "Two cohorts of incident peritoneal dialysis patients were identified according to the time before and after relaxation of the NHI’s erythropoietin payment criteria, designated cohort 1 (n=1759) and cohort 2 (n=2981), respectively." (PMID 33331829, 2020). "Compared with the control group, the expression of EPO and EPOR in the kidney of rats with renal failure was significantly decreased (p < 0.05)." (PMID 31915448, 2019). "We show that even mild renal failure blunts erythropoietin production and propose the HBS1L-MYB locus as a regulator of erythropoietin." (PMID 25915923, 2015). "Animal studies examining acute kidney injury, including ischaemia reperfusion injury (IRI) have shown functional improvements, and anti-inflammatory effects after EPO administration, either before, during, or very importantly, after the injury has taken place." (PMID 25643790, 2015). "The shorter stay study with the longest median LOS (about 10 days) also demonstrated a blunted erythropoietin response in ICU patients, which is aggravated by renal failure." (PMID 17002795, 2006). "The chronically transfused patients were so aware of this risk that Dr. Eschbach had no problem recruiting large numbers of patients with kidney failure in Seattle for the EPO studies." (PMID 38672425, 2024). "In 2005, a retrospective study showed that EPO treatment in acute renal failure patients did not lower the transfusion requirements, the renal recovery or patient survival." (PMID 35279078, 2022). "Analyzing serum EPO levels in a larger cohort of patients with HUS and acute kidney injury of other origins may help to further elucidate whether the degree of renal dysfunction and/or injury correlates with the endogenous EPO production." (PMID 36211426, 2022). "Hypoxia, inflammation, and oxidative stress promote the trans-differentiation of resident fibroblasts, renal erythropoietin-producing cells, or pericytes to extracellular matrix (ECM)-producing myofibroblasts, ultimately leading to renal failure with exacerbation of global fibrosis." (PMID 33453410, 2021). "In conclusion, these results showed that concomitant administration of EPO and IPC along with NAC posttreatment may have an additive beneficial effect on kidney IR injury during IR-induced acute renal failure." (PMID 31342735, 2019). "CEPO improves renal function and survival in acute kidney injury models without raising hematocrit levels and blood pressure as substantially as EPO." (PMID 30258396, 2018). "In this study, the authors compared 20 patients with CKD who were treated with erythropoietin with 43 patients who had a similar degree of renal failure but who were less anemic and thus did not receive erythropoietin." (PMID 25340147, 2013). "Critically ill patients (acute kidney injury and non-acute kidney injury patients) had higher serum levels of erythropoietin than the other groups." (PMID 24488387, 2013). "•Intravenous administration of a pre-emptive single bolus of 300 IU/kg of EPO did not decrease the incidence of acute kidney injury." (PMID 24156702, 2013). "As IL6 is emerging as a predictive factor for acute kidney injury and adverse post-operative outcomes, the absence of a beneficial effect of EPO on its levels parallels the unchanged incidence of acute kidney injury and mortality." (PMID 23033926, 2012). "A significant inverse correlation between hematocrit and EPO was found in the control patients and in the nonseptic patients without renal failure." (PMID 15987387, 2005). "The correlation of EPO with hematocrit was lost in the septic patients and in the nonseptic patients with acute renal failure." (PMID 15987387, 2005). "However, the clinical use of erythropoietin in LPI has been limited to patients in advanced stages of renal failure, typically during dialysis, with no discernible improvement in hematological complications." (PMID 39881295, 2025).
renal failure (continued). "Although most preclinical studies in animals suggest that EPO could alleviate inflammatory damage and fibrosis progression in the kidneys, clinical observations have not demonstrated a protective effect of EPO on acute kidney injury." (PMID 41179707, 2025). "Thus, patients with more advanced stages of renal failure benefit less from the administration of iron in any of its forms in relation to the erythropoietin deficit, not necessarily in relation to the heart failure condition." (PMID 37109444, 2023). "Meanwhile, the cardioprotective effect of RIPC was absent in rats with renal failure, indicating that insufficient EPO release from kidney may blunt RIPC-induced protection." (PMID 33479330, 2021). "RIPC failed to confer cardioprotection in rats with renal failure, which may be attributed to the lack of EPO release during renal failure." (PMID 30719216, 2019). "The central role of inflammation on EPO production is underscored by the observations that anemic patients without renal failure who have inflammation have relatively decreased levels of serum EPO as compared to levels in similarly anemic patients without inflammation." (PMID 30108502, 2018). "Thus, one could speculate that patients who do not need rHuEPO therapy despite kidney failure, still may have enough endogenous EPO production to maintain normal EPC numbers." (PMID 20628606, 2010).